TFE3 (transcription factor binding to IGHM enhancer 3)
Diseases named in the same sentence as TFE3 in open-access papers (continued):
Sharing a sentence is not in itself a finding about the gene and the disease.
soft tissue tumor (6 papers, 2015 to 2024). "Since relatively few soft tissue tumors are TFE3 positive, TFE3 is fruitful as a diagnostic marker for SFT and can be paired with STAT6 for a more accurate diagnosis." (PMID 38659562, 2024). "TFE3, an oncogenic transcription factor involved in other soft tissue tumor translocations, is upregulated as a consequence of the YAP1::TFE3 fusion." (PMID 36983010, 2023). "In SFT, TFE3 immunohistochemical staining is a useful diagnostic marker and can be combined with STAT6 for better diagnosis, as very few soft tissue tumours are TFE3 positive." (PMID 32566457, 2020). "Furthermore, translocations involving the TFE3 gene with several different partners have been described both in renal and soft tissue neoplasms." (PMID 39410016, 2024).
viral infection (6 papers, 2019 to 2025). "In agreement with our results in iBMDMs, we observed significantly higher levels of phospho-IRF3 and cleaved CASP3 in tfeb tfe3 DKO in response to viral infection, as well as reduced cell viability." (PMID 40195022, 2025). "The expression of 4EBP3 at the protein level showed a significant decrease after TFE3 knockdown with plasmids or viral infection." (PMID 30849994, 2019). "However, monensin treatment or viral infections resulted in a significant translocation of TFE3 from the cytoplasm to the cell nuclei." (PMID 34873243, 2021). "Also, editing of NPC1, NPC2, or TFE3 that functions in endolysosomes had a negligible impact on Sfull virus infection." (PMID 33574281, 2021).
Alzheimer disease (5 papers, 2021 to 2025). A progressive, neurodegenerative disease characterized by loss of function and death of nerve cells in several areas of the brain leading to loss of cognitive function such as memory and language. "Recent investigations have also shown that TFE3 enhances autophagy, promoting the degradation of NLRP3 (NLR family pyrin domain containing 3), thereby inhibiting neuroinflammation in Alzheimer's disease models." (PMID 39759118, 2025). "Another study reported that TFE3 mRNA levels are higher than those of TFEB in human hippocampus tissue, and it further demonstrated that TFE3 but not TFEB plays a prominent role in promoting lysosomal biogenesis and autophagy upregulation in CA1 neurons during Alzheimer’s disease pathogenesis." (PMID 34912803, 2021).
colon cancer (5 papers, 2022 to 2025). "We found that TFE3 was markedly upregulated in colon cancer and had a strong correlation with LINC01606." (PMID 35485210, 2022). "Subsequently, we found a strong correlation between LINC01606 and TFE3 expression in 83 colon cancer patients." (PMID 35485210, 2022). "Consistent with the TCGA data, TFE3 expression was upregulated in colon cancer tissues compared with adjacent normal tissues." (PMID 35485210, 2022). "Furthermore, we detected TFE3 mRNA level in 83 pairs of colon cancer samples and adjacent normal tissue samples." (PMID 35485210, 2022). "Similar results were obtained in HT29 colon cancer cells, where glucose depletion downregulated TFEB but upregulated TFE3." (PMID 41275493, 2025). "Consistent with their reported activation in various cancer types, including colon cancer, we detected basal amounts of TFEB and TFE3 in nuclear fractions of control RKO cells by Western blotting analysis." (PMID 35354596, 2022).
Hepatic steatosis (5 papers, 2016 to 2025). Steatosis is a term used to denote lipid accumulation within hepatocytes. "TFE3 overexpression alleviates hepatic steatosis by activating autophagy and PGC-1α-mediated fatty acid metabolism." (PMID 40137502, 2025). "By enhancing autophagy flux, TFE3 relieves hepatic steatosis via enhancing PPARGC1A-dependent mitochondrial FA β-oxidation." (PMID 37007026, 2023). "Conversely, following 24‐h starvation, Tfe3 KO mice exhibited marked hepatic steatosis as determined by gross inspection, H&E and Oil Red O staining (Fig EV2A and B)." (PMID 28283651, 2017). "In conclusion, TFE3 gene provides a novel insight into the treatment of hepatic steatosis and other metabolic disease." (PMID 26999124, 2016). "TFE3 induces lipophagy and alleviates liver steatosis in mice." (PMID 37007026, 2023). "Furthermore, we demonstrate that the effects of TFE3 on hepatic steatosis dependent on the autophagy-induced lipophagy and PGC1α-mediated fatty acid β-oxidation." (PMID 26999124, 2016). "Therefore, we investigated the role of TFE3 in a cell model of hepatic steatosis." (PMID 26999124, 2016). "Finally, we analyzed whether peroxisome proliferative activated receptor gamma coactivator 1α (PGC1α) was the potential target gene of TFE3 in the regulation of hepatic steatosis using a chromatin immunoprecipitation (CHIP) assay and a luciferase reporter system." (PMID 26999124, 2016).
mesenchymal tumors (5 papers, 2022 to 2026). "Together, our data suggest that TFE3 tRCC represent a spectrum of epithelial to mesenchymal tumors, with high expression of oxidative phosphorylation driven directly by a TFE3 core program." (PMID 40148585, 2025). "These considerations notwithstanding, several questions arise: (a) Is it relevant to distinguish carcinomas and mesenchymal tumors in the context of neoplasms carrying the same TFE3 gene translocation?" (PMID 39410016, 2024). "In this work, we gather the available data regarding the key clinical and pathological features of these TFE3-rearranged renal epithelial and mesenchymal neoplasms." (PMID 39410016, 2024). "In recent years, there has been debate about whether it is appropriate to classify HMB45-positive mesenchymal neoplasms carrying TFE3 rearrangement as PEComa." (PMID 39410016, 2024).
microphthalmia (5 papers, 2021 to 2025). Congenital or developmental anomaly in which the eyeballs are abnormally small. "The Microphthalmia-associated transcription factor family includes the basic helix-loop-helix domain-containing transcription factors MITF, TFE3, TFEB, and TFEC." (PMID 35842725, 2022). "Members of the Microphthalmia-associated transcription factor family (MiT), including MITF, TFE3 and TFEB, play a central role in regulating cellular homeostasis in response to metabolic pressure and are considered master regulators of lysosomal biogenesis." (PMID 35842725, 2022). "Transcription factor E3 (TFE3) is located on the short arm of X chromosome 11.22 and is a microphthalmia family member." (PMID 34660181, 2021). "Translocation RCC, or microphthalmia-associated transcription factor family translocation RCC (MiTF-tRCC), encompasses a rare group of diseases involving translocations affecting the short arm of the X chromosomes and fusions of the TFE3, TFEB, or MITF genes." (PMID 40361453, 2025).
spindle cell carcinoma (5 papers, 2012 to 2024). "Adopting recent knowledge on genetic features, its classification has been revised, involving several novel histological types, that is, mucinous tubular and spindle cell carcinoma and Xp11.2/TFE3 translocations-associated RCC." (PMID 24083046, 2013). "A number of rarer histologic subtypes exists, including multilocular cystic RCC, collecting duct carcinoma, mucinous tubular and spindle cell carcinoma, neuroblastoma-associated RCC, and Xp 11.2 translocation-TFE3 carcinoma, with each making up <1% of RCC." (PMID 23150838, 2012).
tuberous sclerosis (5 papers, 2015 to 2025). Hereditary disease characterized by seizures, intellectual disability, developmental delay, and skin and ocular lesions. "There is precedent, however, for simultaneous activation of TFEB/TFE3 and mTORC1 pathways in disease conditions, as we previously reported for the first time in tuberous sclerosis complex." (PMID 38386415, 2024). "Ultimately, future studies will reveal whether Tfeb and/or Tfe3 deletion is sufficient to reduce renal tumorigenesis in mice with spontaneous or inducible loss of Tsc2, and establish whether MiT/TFE targeting could be therapeutically useful in the setting of human tuberous sclerosis." (PMID 36357396, 2022).
angiomyolipoma (4 papers, 2017 to 2025). A neoplasm with perivascular epithelioid cell differentiation often associated with tuberous sclerosis. "Indeed, MITF is considered a hallmark gene of lymphangioleiomyomatosis (LAM) and angiomyolipomas in TSC44,45, based on upregulation of genes that are known transcriptional targets of MITF/TFE3/TFEB/TFEC including MelanA and Cathepsin K46,47." (PMID 38195686, 2024). "Typically, MelanA is expressed in angiomyolipoma (AML), TFE3-rearranged RCC (TFE3-RCC), and TFEB-altered RCC (TFEB-RCC)." (PMID 40584698, 2025).
Ewing sarcoma (4 papers, 2016 to 2024). A small round cell tumor that lacks morphologic, immunohistochemical, and electron microscopic evidence of neuroectodermal differentiation. "Controls (two Ewing sarcomas, two clear cell sarcomas) had no TFE3 and scant nuclear VCP immunofluorescence." (PMID 38326311, 2024).
glioblastoma (4 papers, 2022 to 2026). The most malignant astrocytic tumor (WHO grade IV). "The expression of TFE3 in astrocyte cell lines and glioblastoma cell lines was also detected by RT-qPCR and Western blot." (PMID 35269968, 2022). "According to Western blot, TFE3 was up-regulated in glioblastoma cell lines, especially in LN229 and A172." (PMID 35269968, 2022). "It was found that only TFE3 could stably regulate the expression of HOXD-AS2 in two glioblastoma cell lines, LN229 and A172." (PMID 35269968, 2022). "Therefore, we hypothesized that TFE3 was the transcription regulator upstream of HOXD-AS2 in glioblastomas." (PMID 35269968, 2022). "We then examined the effect of TFE3 on cell proliferation by MTS (3-(4,5-Dimethylthiazol-2-yl)-5-(3-carboxymethoxyphenyl)-2-(4-sulfophenyl)-2H-tetrazolium) assay and found that the proliferation of glioblastoma cell lines, A172 and LN229, also decreased after knocking down TFE3." (PMID 35269968, 2022).
Nephroblastoma (4 papers, 2013 to 2024). An embryonal neoplasm characterized by the presence of epithelial, mesenchymal, and blastema components. "As candidates of differential diagnoses, conventional papillary RCC, mucinous tubular spindle cell carcinoma (MTSCC), Xp11.2/TFE3 translocations-associated RCC, nephroblastoma (especially epithelial type), neuroendocrine carcinoma, and metastatic thyroid papillary carcinoma should be evaluated." (PMID 24083046, 2013).
ovarian carcinoma (4 papers, 2023 to 2025). A malignant neoplasm originating from the surface ovarian epithelium. "Collectively, regulation of SHMT2 isoform expression via alternative promoter usage by transcription factors HIF1α and TFE3 provides a novel basis and potential drug targets for the clinical treatment of platin-resistant ovarian cancer." (PMID 40097394, 2025). "The current study reported that HIF1α and TFE3 were implicated in the utilization of SHMT2 alternative promoter, resulting in expression of SHMT2 isoforms in cisplatin-resistant ovarian cancer cells under metabolic stress." (PMID 40097394, 2025). "PLA analyze confirmed the enhanced interaction of TFE3 and HIF1α in cisplatin-resistant ovarian cancer cells under the low-glucose and hypoxic condition." (PMID 40097394, 2025). "Identification of selective utilization of SHMT2 alternative promoter by the combination of HIFα and TFE3 in cisplatin-resistant ovarian cancer cells in the current study further strengthen the complicated interlinkage between hypoxia and SHMT2." (PMID 40097394, 2025). "Selective utilization of SHMT2 alternative promoter by HIF1α and TFE3 resulted in SHMT2 isoform expression shift, which might be implicated in adaptation of ovarian cancer cells under metabolic stress." (PMID 40097394, 2025). "Interestingly, using an additional ovarian cancer cell line we observed that inhibition of PP2A using calyculin A resulted in a significant upregulation of phosphorylated TFE3 with unique nuclear retention." (PMID 39349971, 2024). "In addition, the current study demonstrated that SHMT2 alternative promoter usage mediated by HIF1α and TFE3 might represent adaptive response of ovarian cancer cells to metabolic stress." (PMID 40097394, 2025). "The treated TFE3-RCC cells demonstrated a G2/M phase block in the cell cycle and increased apoptosis as was previously observed in ovarian carcinoma cells in response to a Mithramycin A analog." (PMID 37095531, 2023).
pancreatic ductal adenocarcinoma (4 papers, 2020 to 2025). An infiltrating adenocarcinoma that arises from the epithelial cells of the pancreas. "For example, TFE3 has been shown to enhance the number and function of lysosomes, enhanced autophagy, and promote the pathological process of pancreatic ductal adenocarcinoma." (PMID 41450945, 2025).
paraganglioma (4 papers, 2015 to 2025). A benign or malignant neoplasm arising from paraganglia located along the sympathetic or parasympathetic nerves. "Though TFE3 positivity have been reported in paraganglioma but immunopositivity for neuroendocrine markers, with S100 highlighting sustentacular cells, helps differentiate them from ASPS." (PMID 37218666, 2024).
prostate carcinoma (4 papers, 2021 to 2025). A carcinoma that arises from epithelial cells of the prostate gland. "Our mechanistic studies revealed that STEAP4+ myoCAF represent a distinct subtype associated with ENZ resistance in prostate cancer and indicated that TFE3 plays a pivotal role in this resistance mechanism." (PMID 40917018, 2025). "We established TFE3 as a transcriptional regulator of phosphatidylcholine biosynthesis driving ENZ resistance in prostate cancer." (PMID 40917018, 2025). "In normal prostate samples, we found that the major transcription regulators of stemness genes were HOXB4, NFYB, and TFE3, which differed from those in prostate cancer." (PMID 33985534, 2021). "The negative control was prostate cancer, and the positive control was TFE3 translocation-associated PEComa." (PMID 37528481, 2023). "Building upon previous studies in which CAFs were involved in prostate cancer tumorigenesis, our study identifies a subset of innately enzalutamide‐resistant STEAP4+ myoCAF that drive therapy evasion through TFE3‐mediated transcriptional reprogramming." (PMID 40917018, 2025). "Similar to prostate cancer, our study found that both AR and SENP1 were highly expressed in Xp11.2 tRCC, and the transcript activity of the TFE3 fusion could be regulated by SENP1." (PMID 35452181, 2022).
synovial sarcoma (4 papers, 2019 to 2024). "We conducted immunohistochemical staining for TFE3 in all 50 SFTs and observed malignant peripheral neurilemmoma (n = 10), synovial sarcoma (n = 10), spindle cell lipoma (n = 10), dermatofibrosarcoma protuberans (n = 10), and dedifferentiated liposarcoma (n = 10)." (PMID 32566457, 2020). "Taken together, our results indicate that TFE3 is a valuable marker for differentiating DTF from NF, GIST, neurofibroma, leiomyoma, DFSP, synovial sarcoma, SEF, and scar tissue samples." (PMID 31043173, 2019). "All examined cases of malignant peripheral nerve sheath tumour, synovial sarcoma, spindle cell lipoma, and dermatofibrosarcoma protuberans were TFE3 negative." (PMID 32566457, 2020). "The TFE3 expression was negative in all samples of synovial sarcoma, malignant peripheral nerve sheath tumour, dermatofibrosarcoma protuberans, and spindle cell lipoma and weakly positive in 2 of 10 cases of dedifferentiated liposarcoma." (PMID 32566457, 2020). "All studied samples of neurofibroma, synovial sarcoma, sclerosing epithelioid fibrosarcoma and dermatofibrosarcoma protuberans were negative for TFE3." (PMID 31043173, 2019). "All the examined cases of neurofibroma, leiomyoma, sclerosing epithelioid fibrosarcoma, synovial sarcoma and DFSP were negative for TFE3 nuclear staining." (PMID 31043173, 2019).
angiosarcoma (3 papers, 2019 to 2025). A malignant tumor arising from the endothelial cells of the blood vessels. "The IHC panel confirms that both presence of endothelial markers (CD31 and ERG) and lack of TFE3 and CAMTA have high specificity and sensibility for the diagnosis of angiosarcoma of bone, with focal expression of cytokeratin AE1/AE3 in 9% of the cases." (PMID 32616718, 2020). "Although EHE expresses similar molecular markers to angiosarcoma (CD31, CD34, and ERG), angiosarcoma differs greatly from EHE in terms of light microscopy morphology and often exhibits MYC amplification without CAMTA1/TFE3 expression." (PMID 40896782, 2025).
chromophobe renal cell carcinoma (3 papers, 2022 to 2025). Chromophobe renal cell carcinoma is a rare subtype of renal cell carcinoma, originating from the intercalating cells of the collecting ducts and macroscopically manifesting as a well-circumscribed, highly lobulated, solid tumor that is usually diagnosed at an early stage. "CK7, S100A1, and parvalbumin are helpful immunohistochemical markers in the differential diagnosis between chromophobe renal cell carcinoma and TFE3/TFEB-rearranged renal cell carcinoma." (PMID 35980471, 2022).
collecting duct carcinoma (3 papers, 2012 to 2026). "In conclusion, this study retrospectively analyzed the clinicopathological and prognostic data of 105 metastatic nccRCC patients at our centre, including 41 pRCC, 31 TFE3/TFEB-rearranged RCC, 26 unclassified RCC, 3 chRCC, 3 FH-RCC and 1 collecting duct carcinoma." (PMID 41578672, 2026).
Glucose intolerance (3 papers, 2017 to 2024). Glucose intolerance (GI) can be defined as dysglycemia that comprises both prediabetes and diabetes. "Here we show that TFE3 overexpression rescues the obese phenotype and the glucose intolerance in WT as well as Tcfeb LiKO mice fed HFD." (PMID 28283651, 2017).
lysosomal disorder (3 papers, 2014 to 2024). "Overexpression of TFEB and TFE3 has been shown to promote the elimination of storage material and ameliorate the pathological findings of various lysosomal storage diseases." (PMID 28301521, 2017). "Therefore, pharmacological inhibition of TFE3 phosphorylation would promote cellular clearance in Pompe disease as well as in other lysosomal storage disorders." (PMID 25183957, 2014).
neuroendocrine carcinoma (3 papers, 2013 to 2021). A malignant neuroendocrine neoplasm composed of cells containing secretory granules that stain positive for NSE and chromogranin. "Neuroendocrine carcinoma was the first impression, but positivity for synaptophysin, alpha-inhibin, transcription factor enhancer 3 (TFE-3), calretinin (focal), and CD56 (focal) and high Ki-67-labeling proliferating index (>80%) confirmed the diagnosis of ectopic ACC." (PMID 33815299, 2021).
acinar cell carcinoma (2 papers, 2020). "The nuclear expression of β-catenin, SOX-11 and TFE3 positivities are characteristic findings in SPN, but not in PNET and in acinar cell carcinoma." (PMID 31209654, 2020). "TFE3 expression, for example, is very frequent (94%) in SPN, while the pancreatic neuroendocrine tumors (PNET) are positive just in 25%, and the acinar carcinomas are negative." (PMID 31209654, 2020).
cystic kidneys (2 papers, 2022 to 2023). "The knockdown of FLCN in salivary glands and cystic kidneys triggered metabolic reprogramming pathways by modulating PGC1α and TFE3 transcription and the AMPK-mTOR pathway to support cell proliferation." (PMID 35328408, 2022).
dengue (2 papers, 2023 to 2024). "Additionally, Viettri demonstrated that infection with dengue and Zika viruses induces Golgi complex dilatation and translocation of TFE3, indicating Golgi apparatus stress due to heightened demand imposed by virion and NS1 processing and secretion." (PMID 39652582, 2024). "Under Golgi stress conditions, however, TFE3 becomes dephosphorylated and translocates to the nucleus, where it activates Golgi-related genes, for instance when infections with dengue and Zika viruses trigger TFE3 translocation for activating the Golgi stress response." (PMID 37566051, 2023).